FTO (FTO alpha-ketoglutarate dependent dioxygenase)
Diseases named in the same sentence as FTO in open-access papers (continued):
Sharing a sentence is not in itself a finding about the gene and the disease.
Obesity (continued). "We aimed to investigate nesfatin-1 secretion in vitro, in murine adipose cells, and in human adipose fat samples, as well as to assess the link between circulating nesfatin-1 levels, NUCB2 and Fat Mass and Obesity Gene (FTO) polymorphisms, BMI, Eating Disorders (EDs), and pathological behaviors." (PMID 36678225, 2023). "The genetic loci of FTO emits one of the strongest signals reported in GWAS related to obesity and energy balance, implicating FTO in the pathogenesis of excess adiposity, while mutations of the gene cause growth retardation, developmental delay, and facial dysmorphism." (PMID 36986146, 2023). "FTO has been found to play a pivotal role in regulating transcriptome-wide m6A modification of mRNA, and it is one of demethylases that has been associated with metabolic disorders, such as diabetes, obesity, and cardiovascular disease." (PMID 37781923, 2023). "IRX3 is a known functional long-range target of FTO variants associated with obesity." (PMID 37433298, 2023). "Finally, the FTO protein was identified as key risk factor for obesity by other studies (GWAS, variant lowest P-value 0.0053), which is also a known risk for COVID-19 severity." (PMID 36814457, 2023). "For obesity and associated cardiometabolic diseases, the FTO SNVs may explain more of the variance in White individuals, or there may be other yet-to-be-identified risk or protective factors that were not included here." (PMID 38064210, 2023). "FTO gene is associated with obesity, dietary intake, and the risk of colorectal cancer (CRC)." (PMID 37545585, 2023). "Thus, the present work aims to identify and determine associations between genetic variants of FTO with indicators of overweight and obesity in the Mexican population." (PMID 36672899, 2023). "Finally, TaqIA seems to interact with the FTO gene, one of the most strongly associated genetic loci with obesity, influencing dopaminergic pathways connected to obesity-related impaired learning functions, adiposity, and insulin resistance." (PMID 36986146, 2023). "FTO and MC4R SNPs are associated with obesity, and urban living may accentuate the obesogenic effect of the FTO SNP." (PMID 37664850, 2023). "Single Nucleotide Polymorphisms (SNPs) of the Fat mass and obesity-associated (FTO) gene may be associated with obesity by regulating appetite." (PMID 37752455, 2023). "The fat mass and obesity-related (FTO) gene was the first to be associated with polygenic obesity." (PMID 37605223, 2023). "PNLIP and FTO with its associated genes were identified as candidate genes for targeting obesity." (PMID 37808366, 2023). "FTO, originally known for its role in regulating metabolism and energy utilisation, has been closely associated with the regulation of body fat mass and the risk of obesity." (PMID 37822879, 2023). "Also, it has been shown that miRNA-29b and microRNA-21 (miRNA-21) targeting can indirectly downregulate mRNA of the DNA methyltransferase (DNMT) affecting methylation rates and thereby leading to FTO overexpression, ultimately causing obesity." (PMID 37200795, 2023). "FTO is a protein that is associated with human obesity through a gene-finding strategy." (PMID 38698914, 2023). "Variations within the FTO gene have been linked to both obesity and type 2 diabetes mellitus." (PMID 37710301, 2023). "The m6A sites on the transcripts were further determined to be the direct substrates of FTO (fat mass and obesity-associated protein), which removes the m6A mRNA modification of ULK1 transcripts, thus promoting autophagy and prolonging the half-life of ULK1 transcripts." (PMID 37581026, 2023). "Moreover, hsa-miR-15a-5p binds to CCND1, which is a molecule regulated by FTO, a gene identified as a risk gene for obesity." (PMID 37836393, 2023).
Obesity (continued). "In the meantime, m6Am, a terminal alteration generally 2′-O-methylated at the second base close to the 50 cap in mRNA, together with further methylation at the N6 position, has just recently been Identified as a promising target for FTO removal from the human obesity gene, associated with obesity." (PMID 37880673, 2023). "Different polymorphisms of the FTO gene have been consistently associated with obesity." (PMID 37627102, 2023). "Importantly, non-coding variation within introns 1 and 2 of FTO (for fat mass and obesity-associated) which sits 200–500KB downstream of IRX3, provides the strongest genetic association for risk of human obesity." (PMID 37539037, 2023). "Because obesity is a significant risk factor for CVDs, FTO may play an important role in the development and progression of CVDs." (PMID 37238719, 2023). "For example, FTO (fat mass and obesity associated) was discovered to demethylate m6A in DNA or RNA." (PMID 38698914, 2023). "Previous genome-wide association studies revealed a relationship between the FTO gene and obesity." (PMID 37200795, 2023). "Thus, most studies indicate that certain FTO gene polymorphisms affect appetite change and food intake, leading to mass gain and obesity." (PMID 37200795, 2023). "Identification of FTO gene polymorphisms may be useful for the development of individual obesity management strategies, including the recommendation of taking certain foods and supplements." (PMID 37200795, 2023). "Intriguingly, the effect of FTO obesity-risk alleles on cellular respiration was observed in active beige but not in white or inactive beige adipocytes highlighting its exclusive effect in human abdominal SC adipocytes only when they are activated for thermogenesis." (PMID 37416800, 2023). "Investigations have revealed upregulated expression of FTO (fat mass and obesity-associated gene), a known metabolic disease predictor, in both NAFLD patients and animal models and that abnormal hepatic signaling activity of FTO was associated with impaired metabolism in NAFLD." (PMID 37559095, 2023). "We found a total of 172 genes that were expressed more in active as compared to inactive beige adipocytes carrying FTO risk-free variant, whereas only 18 genes were found in the same comparison with obesity-risk genotype carrier cells; nine genes were overlapping in the two comparisons." (PMID 37416800, 2023). "Interestingly, researchers at the University College London Obesity Research Center have shown that the presence of a specific variant of the FTO gene, called rs9939609 A, correlates with a lower feeling of satiety following meals." (PMID 37375686, 2023). "However, adherence to HEI and DASH diets modified the association between FTO genetic variations and obesity phenotypes." (PMID 37697388, 2023). "This study aims to determine the antiobesity activity of Calophyllum soulattri leaves extract (CSLE) on high fat diet-fed rats (HFD) and to predict the molecular docking and pharmacokinetics of selected compounds of Calophyllum soulattri to fat mass and obesity-associated protein (FTO)." (PMID 37259340, 2023). "The first gene discovered associated with obesity was fat mass and obesity (FTO)." (PMID 36717394, 2023). "Moreover, there are also studies that have found associations between the fat mass and obesity associated gene (FTO) and HTN risk, in which BMI plays a moderating role." (PMID 37324619, 2023). "Children at a greater genetic risk for obesity (dose-dependent model of the FTO genotype) demonstrated pronounced brain and behavioral relationships such that genetic risk was associated with heightened sensitivity to high-calorie food images and increased anterior insula activity." (PMID 37145386, 2023). "Several independent studies have shown an association between FTO SNPs and fat mass and obesity." (PMID 36672899, 2023). "FTO gene is known to be associated with obesity and type 2 DM across diverse ethnic backgrounds." (PMID 36894991, 2023).
Obesity (continued). "Certain polymorphisms of the FTO gene implicated in polygenic obesity are accentuated on an environmental background of physical inactivity and overnutrition, highlighting the interaction between genetics and environment in the development of obesity." (PMID 37034567, 2023). "As FTO is known as an obesity-associated protein, we aim to explore whether obese CRC patients are more susceptible to suffering from CRC through dynamic m6A changes." (PMID 37580808, 2023). "The most commonly implicated gene is fat mass and obesity associated gene (FTO)." (PMID 37697388, 2023). "Finally, since the gene product of the fat mass- and obesity-associated gene (FTO) was proposed as regulator for ghrelin levels and ghrelin action, we aimed to elucidate effects of the FTO SNP rs8050136 on ghrelin concentrations." (PMID 37420007, 2023). "Lower serine influx that can result in the decrease of one-carbon unit levels may lead to lower amounts of mitochondrial complex subunits I, II, and IV in active beige adipocytes carrying FTO obesity-risk genotype." (PMID 37416800, 2023). "Previous work using computational reinforcement learning has shown improved learning rates in individuals with obesity, which may extend to at-risk individuals prior to obesity onset via FTO rs9939609 regulation of dopamine-dependent reward learning." (PMID 37145386, 2023). "Previous studies in multiple populations have associated a gene with fat mass and obesity (FTO)." (PMID 36672899, 2023). "These include an increase in inflammatory cytokines that activates bone-resorbing osteoclasts, mutations in the FTO gene, increased osteoblast senescence caused by obesity, and an increased production of bone marrow fat cells at the expense of bone-forming osteoblasts." (PMID 36932377, 2023). "For example, the Fat mass and obesity-associated (FTO) gene plays a crucial role in obesity, and adolescent overweight and obesity are strongly associated with Single Nucleotide Polymorphisms (SNPs) of the FTO gene." (PMID 37752455, 2023). "As it is well established that obesity is a result of a Gene X environment interaction, investigating the mechanisms by which FTO polymorphisms drive body weight gain is critical to understand the pathophysiological underpinnings of overeating and establishing targeted treatment options." (PMID 37223038, 2023). "In the Mexican population, some associations of FTO SNPs with obesity of the SNPs rs1121980, rs17817449, rs3751812, and rs9930506 have been observed in the mestizo population, and rs9939609 and rs1421085 were associated with obesity in the Mayan population." (PMID 36672899, 2023). "The FTO gene shows a strong association with the BMI, obesity risk, and T2DM." (PMID 37888112, 2023). "In addition, we also observed that active beige adipocytes carrying FTO obesity-risk alleles exerted similar transcriptomic profiles as white or inactive beige adipocytes." (PMID 37416800, 2023). "Interestingly, rs9939609 is one of the variants of the FTO gene that has been most researched for its relationship with clinical obesity markers in various populations, including the Mexican child and adult populations." (PMID 36672899, 2023). "However, such causation disappeared after the removal of SNP rs9937053 in FTO, an obesity-related gene." (PMID 36846222, 2023). "The molecular docking and molecular dynamic simulations of the selected potential compounds of Calophyllum soulattri binding to fat mass and obesity-associated protein (FTO) showed that caloxanthone B has the best affinity compared to those of native ligand and Orlistat." (PMID 37259340, 2023). "FTO variants implicated in obesity have been found in diverse populations: rs1421085, rs8050136, and rs9939609 in an Indian population, rs9939609 in a Russian population, rs9939609, rs1121980, and rs1558902 in a Japanese population, and rs9939609 in a Saudi Arabian population." (PMID 36983642, 2023).
Obesity (continued). "The Fat mass and obesity-associated gene (FTO) is thought to be closely related to obesity." (PMID 37710301, 2023). "As compared to risk-free carriers, active beige adipocytes with FTO obesity-risk genotype had lower expression of these thermogenic genes and also that of the neurotrophic factor S100b, which was postulated to stimulate sympathetic axon growth and to play an important role in BAT innervation." (PMID 37416800, 2023). "Also, it is recommended to conduct further studies evaluating the relationship between FT genotype and intake of different micronutrients and macronutrients, as well as the underlying mechanisms of the effects of the FTO gene on appetite and obesity." (PMID 37752455, 2023). "The susceptibility haplotype rs8050136 of fat mass and obesity associated (FTO) gene is a significant gene associated with an increased risk of obesity and CVD with elevated methylation levels; a similar mechanism is hypothesized for rs9939609 polymorphism." (PMID 37008904, 2023). "However, there is a need for further studies to evaluate the underlying mechanisms of the effects of the FTO gene on appetite and obesity." (PMID 37752455, 2023). "The expression levels of alpha-ketoglutarate-dependent dioxygenase lab homolog 5 (ALKBH5) protein and fatty mass and obesity-associated genes (FTO) were determined using real-time fluorescence quantification polymerase chain reaction and the western blot technique, respectively." (PMID 36814204, 2023). "The fat mass and obesity-associated (FTO) protein also play an essential role in postnatal growth." (PMID 37943827, 2023). "This suggests that alterations in key biological processes associated with depression may interact with FTO risk alleles to increase BMI or obesity risk." (PMID 37387537, 2023). "Decreased expression of these genes in active beige adipocytes with FTO obesity-risk alleles may contribute to the downregulation of lipolysis in the SC adipose tissue of affected individuals." (PMID 37416800, 2023). "The fat mass and obesity-associated (FTO) gene polymorphisms may increase food intake, probably leading to a positive energy balance and obesity." (PMID 36263301, 2022). "Expectedly, as the first identified obesity-related gene, FTO polymorphisms affected weight loss." (PMID 35811975, 2022). "Hence, reduction of adipose accumulation through anti-autophagy pathways activated under conditions of FTO deficiency presents a critical strategy to prevent the harmful effects of increasing obesity." (PMID 35794625, 2022). "Another variant, rs1421085 (FTO) was associated with 27 diseases including direct associations with obesity (P = 5.6 × 10−39), type 2 diabetes (P = 8.2 × 10−27), and hypertension (P = 6.4 × 10−9) and inverse with breast cancer (P = 1 × 10−11), and fasciitis (P = 3.1 × 10−4)." (PMID 36376304, 2022). "Single nucleotide polymorphisms in the FTO gene have been described as having a role in obesity." (PMID 36532520, 2022). "Some authors have proposed that FTO may participate in the occurrence of depression by increasing BMI as FTO is an obesity susceptibility gene." (PMID 35528183, 2022). "One such gene is the FTO gene, which has been reported to be associated with obesity." (PMID 34812958, 2022). "In addition, the association between the single nucleotide polymorphism (SNP) rs1421085 at the fat mass and obesity associated (FTO) gene locus and both PDFF and RMR was investigated." (PMID 35295982, 2022). "In our study, we found that AA normal weight children had almost similar methylation in the FTO gene as overweight and obese, signifying a higher gene expression of FTO leading them towards increased risk of obesity while FTO gene methylation for EA normal weight children was extremely lower." (PMID 36360268, 2022). "Our study has several limitations: due to the cross-sectional nature of this investigation, we cannot infer causality regarding the FTO SNPs and obesity, as functional variants are still unknown." (PMID 36235854, 2022).
Obesity (continued). "The FTO risk allele is linked with increased body mass, BMI and other lifestyle factors that may perpetuate an individual’s risk for obesity." (PMID 36278751, 2022). "In this sense, the fat mass and obesity-associated (FTO) gene plays a crucial role in developing PCOS: a recent study showed that the rs1421085, rs17817449 and rs8050136 variants of the FTO gene positively correlate with higher androgens levels and with an obese phenotype." (PMID 35740328, 2022). "Selected ORGs expression, namely the fat mass and obesity-associated (FTO), melanocortin-4 receptor (MC4R), glucosamine-6-phosphate deaminase 2 (GNPDA2), and transmembrane protein 18 (TMEM18) were evaluated in testes and spermatozoa by a quantitative polymerase chain reaction (qPCR)." (PMID 36289871, 2022). "Furthermore, consuming SSB was found to significantly elevate the FTO genetic obesity predisposition risk, while wine consumption was found to significantly reduce the FTO genetic obesity predisposition risk." (PMID 36235854, 2022). "Besides the polymorphism of FTO found in obesity, it also contributed to many other diseases among various populations." (PMID 35923209, 2022). "Moreover, a large number of studies have shown that the gene polymorphism of FTO is closely related to metabolism disorders such as obesity and T2D." (PMID 35528183, 2022). "In addition, variants of the Fat mass- and obesity-associated (FTO) gene show a strong association with obesity and fat mass but are also described to influence the skeletal muscle phenotypes of athletes." (PMID 35937778, 2022). "The fat mass and obesity–associated protein (FTO) has been shown to be involved in obesity; however, its role in NAFLD and the underlying molecular mechanisms remain largely unknown." (PMID 35282837, 2022). "RNAs can be methylated by Methyltransferase-like 3(METTL3), Methyltransferase-like 14 (METTL14) (“writers”), and demethylated by the fat mass- and obesity-associated (FTO) protein and the α-ketoglutarate-dependent dioxygenase alkB homolog 5 (ALKBH5) protein (“erasers”)." (PMID 35346019, 2022). "The FTO of 410.5 kb locates on chromosome 16q12.2, encoding 2-oxoglutarate (2-OG) iron (II)-dependent alpha-ketoglutarate-dependent hydroxylase family dioxygenase with well-described variants linked to obesity and an increased risk of osteoporosis." (PMID 35883424, 2022). "Additionally, murine non-alcoholic fatty liver disease (NAFLD) model and murine chronic liver injury model were utilized to investigate the role of IL-17RA regulated by m6A mRNA modulator fat mass and obesity-associated (FTO) in chronic hepatic inflammation." (PMID 36172147, 2022). "The gene FTO was the first gene identified (through a GWAS) that linked FM and obesity in humans." (PMID 36555722, 2022). "Although the available data indicate that the SNPS associated with obesity are located in the first intron of the FTO gene, it is important to understand exon mutations to evaluate their effects not only on obesity, but also on other genetic diseases, as indicated by some studies." (PMID 34990463, 2022). "However, the FTO gene has been also associated with genetic polymorphisms that affect the individual response to anti-obesity drugs." (PMID 36501129, 2022). "FTO has been recognized as a major genetic factor for obesity risk in different human groups." (PMID 35560161, 2022). "Moreover, TNF-α inhibits the differentiation of mesenchymal stem cells by repressing fat mass and obesity‐associated protein (FTO) expression and FTO-mediated demethylation of Nanog mRNA levels and decreasing Nanog mRNA expression levels." (PMID 35148766, 2022). "Supporting our initial hypothesis, rCBF varied as a function of the FTO allele across several brain regions in adults with overweight or obesity." (PMID 36072887, 2022). "FTO genotype is also associated with individual variability in physiological responses (e.g., weight loss) to diet/lifestyle interventions in populations with overweight and obesity." (PMID 36072887, 2022).